CAV1 (caveolin 1)
Diseases named in the same sentence as CAV1 in open-access papers (continued):
Sharing a sentence is not in itself a finding about the gene and the disease.
prostate carcinoma (continued). "The resistance-promoting effect of Cav1-deficient HS5(−) fibroblasts was further analyzed by determining the degree of apoptosis (SubG1 fraction) after radiation in PC3 (+/−Cav1) and Cav1-deficient LNCaP prostate cancer cells in the presence of HS5 SN." (PMID 28112237, 2017). "Augmented CAV1 expression has been associated previously with progression towards a more aggressive cancer phenotype, for instance for prostate cancer and melanomas, although in those cases the precise mechanisms involved were not defined." (PMID 29340103, 2017). "Low tumor Cav-1 was associated with an increased relative risk for prostate cancer specific death in a univariate Cox regression analysis." (PMID 27764093, 2016). "High expression of Caveolin-1 in tumor stroma was associated with significantly longer cancer specific survival in prostate cancer patients." (PMID 27764093, 2016). "High stromal Caveolin-1 immunoreactivity in prostate tumors is associated with a favourable prognosis in prostate cancer patients managed by watchful waiting." (PMID 27764093, 2016). "Although this and previous studies suggests that decreased stromal Cav-1 is associated with poor prostate cancer prognosis several important questions remain unanswered." (PMID 27764093, 2016). "In another example, a sub-population of FASN in prostate cancer cells associates with lipid rafts and physically interacts with Cav-1, which must be palmitoylated for the interaction to occur." (PMID 26659560, 2015). "Expression of Caveolin-1 (Cav1), a key component of cell surface caveolae, is elevated in prostate cancer (PCa) and associated with PCa metastasis and a poor prognosis for PCa patients." (PMID 25942420, 2015). "Caveolin-1 has been reported to be overexpressed in prostate cancer cells and is associated with disease progression 148,149." (PMID 24629090, 2014). "A growing body of evidences have suggested that Cav-1 is overexpressed and associated with metastatic progression of various cancers including prostate cancer, lung cancer, renal cancer and esophageal cancer." (PMID 24454730, 2014). "The anticancer mechanisms of simvastatin in prostate cancer cells has been associated with inhibition caveolin-1-dependent cell-survival signals, which are mediated via Akt activation." (PMID 24932304, 2014). "Our results analysing human melanocytes and different stages of melanoma progression suggest that CAV1 expression is linked to increased metastatic potential 7 and follows a pattern similar to that reported previously for prostate cancer." (PMID 24500501, 2014). "The results implied the tumor inhibiting role of CAFs Cav-1 protein and were consistent with the finding in breast and prostate cancer, which elucidated that loss of stromal Cav-1 heralds poor prognosis." (PMID 23527097, 2013). "Conversely, cav-1 is consistently up-regulated in bladder cancer, esophageal cancer and prostate carcinomas, and this up-regulation has been associated with metastases and poor prognosis in prostate carcinoma and esophageal squamous cell carcinomas (SCC)." (PMID 22200856, 2012). "Alternatively, augmented caveolin-1 expression has been associated with enhanced metastatic potential and migration of lung and prostate cancer cells." (PMID 22505999, 2012). "Loss of stromal Cav-1 is predictive of recurrence, metastasis, and poor clinical outcome, and as such is a new biomarker for breast and prostate cancer." (PMID 21605374, 2011). "Substantial evidence of increased expression of Cav-1 associated with tumour progression and metastasis has been established mostly in prostate cancer." (PMID 19002186, 2008). "Although CAV1 expression is increased in prostate cancer, oesophageal cancer and ovarian cancer, future studies should include assessment of CAV1 mutation." (PMID 15305200, 2004). "Previous studies have implicated Cav1 in a paracrine antiapoptotic loop in prostate cancer PNI46." (PMID 41330921, 2025).
prostate carcinoma (continued). "Dysregulation of the Cav1 gene shows a notable association with prostate cancer." (PMID 37910338, 2023). "Moreover, caveolin-1 is also associated with c-Myc in prostate cancer and KD of CFTR lead to increased inflammation and caveolin-1 levels." (PMID 35500936, 2022). "CAV1 has been associated with radioresistance in both lung and prostate cancer." (PMID 35660849, 2022). "Caveolin-1 is reportedly overexpressed in prostate cancer and could serve as a risk factor and adverse clinicopathological feature of PCa." (PMID 34503059, 2021). "In parallel, a loss of stromal CAV1 could be observed, which correlated with tumor progression and therapy resistance, especially in prostate cancer (PCa), and may therefore be suited as a prognostic marker." (PMID 32273493, 2020). "Plasma and tumor caveolin-1 (Cav-1) are linked with disease progression in prostate cancer." (PMID 32855410, 2020). "Our results add to this picture by highlighting how, in prostate cancer cells, palmitic acid determines the exosome-associated content of the metastatic progression marker and exosomal secretion molecule caveolin 1 and prostate cancer-associated exosomal motor protein myosin IC." (PMID 32545453, 2020). "However, a detailed mechanism explaining how CAV1-deficient fibroblasts foster therapy resistance of malignant prostate cancer cells remains elusive." (PMID 30871022, 2019). "Our results strongly argue for a Cav1-dependent EMT in prostate cancer progression which is closely linked and thus may account for the observed radiation resistance." (PMID 28112237, 2017). "In prostate cancer stroma, loss of CAV1 associated with reduced relapse-free survival." (PMID 29190968, 2017). "The few patients (7%) with low tumor Cav-1 and high tumor PDGFRβ had an approximately 3-fold excess risk of prostate cancer death compared to the added separate relative risks for patients identified as having low tumor Cav-1, or high tumor PDGFRβ respectively (interaction analysis P <0.001)." (PMID 27764093, 2016). "Caveolin-1 is overexpressed, and is associated with disease aggressiveness in prostate cancer." (PMID 24727247, 2014). "Caveolin-1 (Cav-1) expression deficiency and autophagy in tumor stromal fibroblasts (hereafter fibroblasts) are involved in tumor proliferation and progression, particularly in breast and prostate cancer." (PMID 23203033, 2012). "The second question we wanted to answer was whether the expression of CAV1 gene in prostate cancer cells reflects their bio-mechanical phenotypes because Cav1 has been recently linked to cell stiffness through the regulation of actin remodelling and focal adhesions." (PMID 30733487, 2019). "Therefore treatment with Src inhibitors might be a potential treatment option for radiosensitizing advanced prostate carcinomas which were characterized by a Cav1-deficient reactive tumor stroma." (PMID 28112237, 2017). "A number of studies have explored the associations between CAV-1 genetic polymorphisms and the risk of various cancer types including hepatocellular carcinoma, gastric cancer, esophageal cancer, colorectal cancer, renal cell carcinoma, prostate cancer, bladder cancer and leukemia." (PMID 29207674, 2017). "However, caveolin-1 levels are elevated in prostate cancer and lung adenocarcinomas, and the elevated caveolin-1 levels are associated with increased metastatic capacity and poor prognosis, indicative of an oncogenic role for caveolin-1." (PMID 22505926, 2012). "In prostate cancer cell lines, CAV1, PALLD, and ITGB8 are upregulated, while CLDN7 is downregulated." (PMID 40002724, 2025). "Serum caveolin-1 (CAV1) levels have been shown to correlate with tumor stage, grade, angiogenesis, and poor prognosis in prostate cancer patients." (PMID 39893499, 2025). "And yet, with the development of prostate cancer, there is an increase in the levels of cav-1 expression which promotes the further progression of metastatic cancer." (PMID 39857963, 2025).
prostate carcinoma (continued). "Prostate-specific membrane antigen (PSMA) and caveolin-1 are membrane proteins that are overexpressed in prostate cancer (PCa) and are involved in tumor growth and increase in aggressiveness." (PMID 38542507, 2024). "Similar data were observed in prostate cancer, where high CAV1 expression correlates with advanced disease and reduced survival after surgery." (PMID 39596307, 2024). "We demonstrate that there is an increase in the expression of clathrin with increasing Gleason score in prostate cancer and a concurrent decrease in caveolin-1 expression." (PMID 36869937, 2023). "It has been reported that inhibition of Cav1 expression can change the insensitivity of androgen-insensitive prostate cancer cells to androgen and slow down the progression of PCa." (PMID 37910338, 2023). "We identified two major CAFs subtypes with distinct molecular characteristics and biological functions in prostate cancer microenvironment, namely αSMA+ CAV1+ CAFs-C0 and FN1+ FAP+ CAFs-C1." (PMID 37033924, 2023). "Conversely, there was a significant (p < 0.0001) decrease in expression of caveolin-1 in prostate cancer tissue compared to normal prostate tissue." (PMID 36869937, 2023). "Our results show a concurrent and opposite change in the expression of these clathrin and caveolin-1 proteins in prostate cancer and as the cancer progresses towards aggressive disease." (PMID 36869937, 2023). "Nevertheless, there is no systematic review to report about molecular signal mechanism of Cav1 and drug treatment in prostate cancer." (PMID 37910338, 2023). "We discovered two major CAFs subtypes in prostate cancer microenvironment, termed αSMA+ CAV1+ CAFs-C0 and FN1+ FAP+ CAFs-C1." (PMID 37033924, 2023). "Cav1 mainly affects the occurrence of prostate cancer through AKT/mTOR, H-RAS/PLCε, CD147/MMPs and other pathways, as well as substance metabolism including lipid metabolism and aerobic glycolysis." (PMID 37910338, 2023). "Caveolin-1 was found upregulated in tumors characterized by an aggressive, metastatic phenotype, and its expression in prostate cancers correlates with poor prognosis." (PMID 37516753, 2023). "In cluster 2, “caveolin-1” was the largest node, the other main nodes included metastasis, progression, survival, overexpression, prostate-cancer, and adenocarcinoma." (PMID 37576808, 2023). "A study in prostate cancer showed that epithelial expression of Cav1 was higher in black men when compared to white men." (PMID 37822942, 2023). "Knockdown of CAV-1 in breast and prostate cancer cells reduced the velocity, directionality, and persistency of cellular migration." (PMID 37516753, 2023). "In this manner, LRP6 and CAV1 stimulate aerobic glycolysis by increasing the expression of glycolytic enzymes in prostate cancer cells." (PMID 35740528, 2022). "Alternatively, in prostate cancer cells, CAV1 interacts with LRP6 to stimulate the IGF-IR/IR/Akt/mTORC1 pathway and promote glycolysis by increasing the expression of glucose transporters and glycolytic enzymes." (PMID 35740528, 2022). "CAV1 (caveolin 1) alters lipid metabolism in prostate cancer cells that, subsequently, stimulates mitophagy as a lethal process." (PMID 35317831, 2022). "In the present study, the results indicated that CAV1–3 were all significantly downregulated in most tumor types, especially in BC, lung cancer, ovarian cancer, prostate cancer, and sarcoma cancer." (PMID 36147736, 2022). "For instance, expression of Cav-1 in LOs is known to be an indicator of metastatic disease in prostate cancer patients." (PMID 36045692, 2022). "CAVIN1 expression is decreased during prostate-cancer progression and is strongly correlated with that of CAV1 in prostate-cancer cells and tumors." (PMID 35158857, 2022).
prostate carcinoma (continued). "In prostate cancer, non‐caveolar caveolin‐1 (CAV1) promotes metastasis, while CAVIN1 attenuates CAV1‐induced metastasis." (PMID 33931969, 2021). "The expression pattern CAV1+/CAVIN1‐ is replicated in the non‐caveolar PC3 (aggressive prostate cancer) cell line." (PMID 33931969, 2021). "Metastatic potential of prostate cancer can be related to caveolin-1 (CAV1), member of caveolin family of proteins." (PMID 33673178, 2021). "For example, a tumor-promoting role of caveolin-1 has been found in renal and prostate cancers and in lung and bladder squamous cell carcinomas (SCCs)." (PMID 33037799, 2021). "CAV1 was found to activate AKT in prostate cancer, and potentially other malignancies, finally leading to the increased phosphorylation of multiple AKT substrates that mediated increased cancer cell invasiveness." (PMID 33868995, 2021). "This study utilised non‐caveolar CAV1 in aggressive prostate cancer cells as a model system to investigate the molecular mechanisms of miRNA loading to EVs." (PMID 33931969, 2021). "An inverted CAV1 topology defines novel autophagy-dependent exosome secretion from prostate cancer cells." (PMID 34234869, 2021). "In summary, we have identified a Cav-1-sphingolipid signature as a significant independent prognostic indicator of disease progression in prostate cancer." (PMID 32855410, 2020). "Low and Nicholson reviewed the effect of epigenetic regulation of CAV1, concluding that hypermethylation of the CAV1 promoter decreases protein levels in breast and prostate cancer." (PMID 32458269, 2020). "The integral membrane protein caveolin-1 (CAV1) plays a central role in radioresistance-mediating tumor–stroma interactions of advanced prostate cancer (PCa)." (PMID 32273493, 2020). "Furthermore, elucidation of the mechanistic basis underlying this lipid oncometabolism yields a Cav-1 sphingolipid signature that is detectable in blood and that may be indicative of disease progression in subjects with early stage prostate cancer who are enrolled on active surveillance." (PMID 32855410, 2020). "We also demonstrate, using a prostate cancer syngeneic RM-9 mouse model and established cell lines, that this Cav-1-sphingolipid program evidences a metabolic vulnerability that is targetable to induce lethal mitophagy as an anti-tumor therapy." (PMID 32855410, 2020). "Through the application of bioinformatics technology, we identified the potential key genes associated with the occurrence and development of prostate cancer as FGF2, FLNA, VCL, FLNC, CAV1, ACTC1, and MYLK." (PMID 32547947, 2020). "Cav-1 has been suggested to play a role in the perturbation of a number of metabolic pathways in prostate cancer cells." (PMID 32855410, 2020). "On the basis of these mechanistic findings, we test for potential actionable metabolic vulnerabilities by targeting Cav-1-mediated lipid scavenging and metabolism in a mouse model of aggressive prostate cancer." (PMID 32855410, 2020). "Our results also suggest some role of CAV1 in the total stiffness of prostate cancer cells and a positive correlation between cell stiffness and cell dry mass in the non-treated cells and between cell stiffness and cell dry mass density in the treated cells." (PMID 30733487, 2019). "In prostate, CAV1 is not present in normal tissue, but expression increases along with the development of cancer in mouse and human models and in vitro, CAV1 promotes metastatic features of prostate cancer cells." (PMID 31362353, 2019). "Thompson and colleagues were the first to show that CAV1 is secreted by prostate cancer cells in a manner regulated by steroid hormones." (PMID 31362353, 2019). "Secretion and overexpression of Cav1 in prostate cancer promotes tumor growth and has significant role in cancer metastasis." (PMID 31449531, 2019). "CAV1 was detected in serum from patients with advanced prostate cancer and to a significantly lesser extent in normal subjects." (PMID 31362353, 2019).
prostate carcinoma (continued). "We validate our methods on a dataset of super-resolution microscopy images of PC3 prostate cancer cells labeled for Cav1." (PMID 31449531, 2019). "At present, caveolin-1 can be detected in the peripheral blood, and its expression level can be used to improve the diagnosis of prostate cancer and is related to prognosis." (PMID 30424755, 2018). "The higher the differentiation of the prostate cancer tissue was, the stronger the staining intensity of caveolin-1, the higher the percentage of positive cells, and the higher the positive rate were." (PMID 30424755, 2018). "CAV1 plays dual roles in the progression of breast, lung, cervical, gastric, glioma liver, and prostate cancers." (PMID 30333750, 2018). "Cav-1 has been reported as a marker for LOs, and results suggest that Cav-1 positive LOs can be used to detect metastatic disease in patients with prostate cancer." (PMID 29760691, 2018). "In this study, caveolin-1 was detected in pathological tissue slices of prostate cancer by streptavidin-peroxidase (SP) immunohistochemical staining." (PMID 30424755, 2018). "Caveolin-1 can be used as a biologically active molecule to promote tumorigenesis and tumor angiogenesis in the prostate cancer microenvironment." (PMID 30424755, 2018). "In contrast, there are also number of malignancies where CAV1 was found to be overexpressed e.g. pancreatic adenocarcinoma, prostate cancer, non-small cell lung carcinoma, renal cell carcinoma (RCC) and glioblastoma." (PMID 29719615, 2018). "The high expression of caveolin-1 is closely related to prostate cancer, promoting the occurrence, progression, and infiltration of the tumors." (PMID 30424755, 2018). "Caveolin-1 is upregulated in prostate cancer, and its high expression in most prostate cancer tissues can promote the proliferation of cancer cells and metastasis to lymph nodes." (PMID 30424755, 2018). "In this study, the expression of caveolin-1 was significantly higher in prostate cancer than in benign prostatic hyperplasia." (PMID 30424755, 2018). "In this study, it was found that high caveolin-1 expression is closely related to prostate cancer after transurethral surgery and has a role in promoting tumorigenesis, development, and infiltration." (PMID 30424755, 2018). "In conclusion, caveolin-1 is highly expressed in prostate cancer and is closely related to the pathological grade and clinical stage of prostate cancer." (PMID 30424755, 2018). "Caveolin-1 positive staining was found in the cell membrane and cytoplasm of prostate cancer (PCa) cells, presenting as yellowish-brown or brown particles." (PMID 30424755, 2018). "Application of machine learning to point cloud SMLM network analysis of Cav1 distribution in PC3 and PC3-PTRF prostate cancer cells has now defined Cav1 localization signatures for scaffolds and caveolae." (PMID 29899348, 2018). "From these results, it is proposed that the neddylation of caveolin-1 stops cell migration at least in prostate cancer and glioblastoma by counteracting the Src-caveolin-1 pathway." (PMID 29301501, 2018). "The current research aims to investigate caveolin-1 expression in prostate cancer tissue and its relationship with pathological grade, clinical pathologic staging, and preoperative prostate-specific antigen (PSA) levels." (PMID 30424755, 2018). "The difference in caveolin-1 expression was significant for different clinical stages (T1-T2 and T3-T4) of prostate cancer (P < 0.05)." (PMID 30424755, 2018). "It is also believed that caveolin-1 activates the PI3-K-Akt signaling pathway in prostate cancer cells and promotes cancer cell metastasis by interacting with transfer molecules such as VEGF, TGF-β1 and FGF2." (PMID 30424755, 2018). "The difference between the two groups was statistically significant, suggesting that caveolin-1 was related to prostate cancer invasion (P < 0.05)." (PMID 30424755, 2018).